RIPK3 (receptor interacting serine/threonine kinase 3)
Diseases named in the same sentence as RIPK3 in open-access papers (continued):
Sharing a sentence is not in itself a finding about the gene and the disease.
Sepsis (continued). "Receptor-interacting protein kinase 3 (RIPK3)-dependent necrosis is implicated in driving tumor necrosis factor alpha (TNF-α)- and sepsis-induced mortality in mice." (PMID 24996547, 2014). "In conclusion, data provided in this study show that RIPK3 plays a role in altering sepsis-induced immune cell trafficking in an organ-specific manner and its deficiency attenuates organ damage as well as modestly prolongs survival." (PMID 24996547, 2014). "Thus, RIPK3 played a crucial role in altering immune cell trafficking during sepsis, which may suggest targeting RIPK3 as a therapeutic strategy in attenuating organ injury caused by excessive immune cell infiltration in sepsis." (PMID 24996547, 2014). "Importantly, necroptosis mediated by RIPK1 and RIPK3 significantly contributes to the increased mortality observed during sepsis." (PMID 40817040, 2025). "However, recent studies have demonstrated that deficiency of RIPK3 or gasdermin D (GSDMD) can protect against TNF-induced SIRS, CLP-induced sepsis, or lipopolysaccharide (LPS)-induced septic shock." (PMID 38684668, 2024). "Inhibition of RIPK3 with siRNA limits gut epithelial necroptosis and protects against colitis, an approach that could theoretically limit the gut barrier damage of sepsis and prevent ongoing immune stimulation." (PMID 38274794, 2023). "A study on sepsis-associated encephalopathy indicated that STING expression in hippocampal neurons is elevated and interacts with PERK, a significant factor of ER stress, to promote p-RIPK3/RIPK3 expression in damaged neurons." (PMID 37915571, 2023). "A recent in vivo study using LPS‐stimulated human kidney tubular epithelial cells showed increased RIPK3 expression, with enhanced insights into the unique role of RIPK3 in regulating mitochondrial function during sepsis, as evidenced by observations of mitochondrial depolarization in vitro." (PMID 38020710, 2023). "One study explored how Ripk3 levels affected cardiac dysfunction induced by sepsis, and whether melatonin could improve it and the molecular mechanism." (PMID 35795371, 2022). "Ripk3 promoted mitochondrial dysfunction, which increased sepsis-induced kidney damage." (PMID 35795371, 2022). "Ripk3 appears to be able to reduce damage to mitochondria as well as ER stress, and could also affect sepsis-induced cardiac injury." (PMID 35795371, 2022). "RIPK3, a mediator of necroptosis, has been reported to be involved in sepsis-induced AKI." (PMID 36188562, 2022). "Inhibition of RIPK3 attenuated tubular damage and improved renal function in sepsis-induced AKI." (PMID 36188562, 2022). "Moreover, RIPK3 contributes to tubular injury and renal insufficiency in sepsis-mediated acute kidney injury (AKI) by inhibiting TEFB expression." (PMID 35402535, 2022). "Our study of 190 consecutively enrolled critically ill patients demonstrated that the plasma TRAIL level was inversely associated with sepsis severity and plasma level of RIPK3; however, it was not predictive of mortality." (PMID 32492832, 2020). "Plasma levels of TRAIL increased over time on days three and seven, and were inversely associated with sepsis severity and RIPK3 level, but not with mortality." (PMID 32492832, 2020). "The kinetics of plasma RIPK3 in the early hours of sepsis and trauma remain unclear, as does the ability of RIPK3 at such time points to predict subsequent ARDS." (PMID 31253195, 2019). "The change in plasma RIPK3 from presentation to 48 h in both sepsis and trauma patients is independently associated with ARDS, and plasma RIPK3 may reflect RIPK3 activity in lung tissue." (PMID 31253195, 2019). "We hypothesized that plasma RIPK3 concentrations in sepsis and trauma would be associated with ARDS development and that plasma RIPK3 would reflect changes in lung tissue RIPK3 in a murine model of systemic inflammation." (PMID 31253195, 2019).
Sepsis (continued). "The RIPK3 levels in severe sepsis and septic shock group were markedly higher than those in sepsis group at various time points (all p < 0.05), and trends were remarkably similar for SOFA scores, CRP levels, and PCT among these groups but not RIPK1 levels and WBC counts." (PMID 29137405, 2017). "Additionally, plasma RIPK3 levels, APACHE II score, SOFA score, PCT level, and the number of organs exhibiting dysfunction were association with a poor prognosis in sepsis patients." (PMID 29137405, 2017). "In conclusion, our results have some clinical insights that the plasma RIPK3 level may have promising value for the prognostic of sepsis, and its application could be matched by that of the SOFA score and PCT level." (PMID 29137405, 2017). "The experiments reported in this paper demonstrate that although RIPK3 is involved in the pathogenesis of other diseases, including sepsis, lung and renal ischemia/reperfusion, the pathways engaged by RIPK3 are not crucial to the development of autoimmunity or immune mediated nephropathies." (PMID 27669412, 2016). "Hence, determining the effects of ablation of RIPK3-mediated necrosis on the trafficking of various subtypes of immune cells and resultant organ injury following sepsis is critical for the development of therapies for patients." (PMID 24996547, 2014). "Moreover, using a clinically relevant model, they have alsosuggested that RIPK3 deficiency also protected against CLP-induced sepsis,underscoring the clinical relevance of RIPK inhibition in sepsis." (PMID 25412304, 2014). "• RIPK3 deficiency attenuates CLP-induced organ injury by inhibiting the infiltration of immune cells in an organ-specific manner and, thus, protects against sepsis." (PMID 24996547, 2014). "In this study we report for the first time an increase in the hepatic NK cell population after CLP-induced sepsis specifically in the liver (not seen in lungs) which is attenuated after RIPK3 deficiency." (PMID 24996547, 2014). "Interestingly, our study shows that RIPK3 deficiency results in a liver specific combined decrease in NK and CD8T cells after sepsis." (PMID 24996547, 2014). "The discrepancies of these two reports establishing therole of RIPK3 in sepsis might be due to various natures of luminal bacteria that wereunique to the experimental animals housed in a particular animal facility." (PMID 25412304, 2014). "In the light of these observations we propose that RIPK3 deficiency attenuates CLP-induced organ injury by inhibiting the infiltration of immune cells in an organ-specific manner and, thus, protects against sepsis." (PMID 24996547, 2014). "In addition, the number of natural killer (NK) and CD8T cells in the liver decreased by 64.8% and 53.4%, respectively, in Ripk3-/- mice compared to WT mice post-sepsis." (PMID 24996547, 2014). "Necroptosis effector genes are markedly upregulated with increased RIPK1, RIPK3, and MLKL co-expression evident in spinal GABAergic neurons, while administration of the necroptosis inhibitor Necrostatin-1 substantially preserves neurons and reverses sepsis-associated cardiac functional changes." (PMID 40692211, 2025). "RIPK3 could enhance sepsis-induced kidney injury by promoting mitochondrial dysfunction." (PMID 37091800, 2023). "We hypothesized that plasma RIPK3 levels would be associated with ARDS in both sepsis and trauma populations, independent of patient-level characteristics." (PMID 31253195, 2019). "In addition, RIPK3 levels in severe sepsis and septic shock patients peaked at 72 hours and afterwards declined gradually, which might suggest that inflammation in those two groups was at the highest levels by 72 hours." (PMID 29137405, 2017). "In the present study, using RIPK3-deficient (Ripk3-/-) mice in a physiologically relevant model of severe polymicrobial sepsis induced by cecal ligation and puncture (CLP), we examined the role of RIPK3 in altering immune cell trafficking and organ injury in sepsis." (PMID 24996547, 2014).
Sepsis (continued). "Thus, RIPK3 acts as a detrimental factor in contributing to the organ deterioration in sepsis." (PMID 24996547, 2014). "Our study uncovers a role for RIPK3/caspase-8 signaling in regulating obesity-induced inflammation, independent of its capacity to activate NLRP3, aligning with recent reports in sepsis and arthritis models." (PMID 39532538, 2025). "C57BL/6 wild type (WT), Casp8−/−, Ripk3−/−, and Zbp1−/− mice were subjected to the cecal ligation and puncture (CLP) sepsis model." (PMID 39465383, 2024). "RIPK3 upregulates NOX4 and promotes sepsis-induced AKI by inducing oxidative stress and mitochondrial dysfunction." (PMID 37627536, 2023). "Previous studies have demonstrated that that the classical pathway of necroptosis, RIPK1/RIPK3 pathway, can collaborate with the key protein of pyroptosis, GSDMD, to amplify inflammatory signals and exacerbate tissue damage during sepsis." (PMID 38161332, 2023). "In sepsis-AKI, RIPK3 aggravated kidney injury in a MLKL-independent manner by promoting mitochondrial dysfunction via NOX4 upregulation, but the contribution of tubular cell death was not clearly demonstrated." (PMID 38077379, 2023). "We found significantly higher expression of RIPK1, RIPK3, and MLKL in the peripheral blood nucleated cells of sepsis patients than controls." (PMID 36765040, 2023). "Studies have reported elevated levels of RIPK3 in the plasma and urine of sepsis-induced AKI patients, and RIPK3 expression is also higher in AKI kidneys with tubular injury in human biopsy samples." (PMID 38054182, 2023). "In a sepsis-induced AKI model, mice subjected to CLP surgery showed elevated levels of pRIPK3, in addition to this RIPK3, which were observed in renal tubular epithelial cells." (PMID 36361505, 2022). "To our knowledge, we have demonstrated, for the first time, the association of plasma levels of surrogate markers of necroptosis activity RIPK3 and MLKL, with that of HMGB1 in patients with sepsis." (PMID 33947887, 2021). "When correlation between TRAIL and RIPK3 was assessed, the plasma level of TRAIL was inversely related to the plasma level of RIPK3 in patients with sepsis and septic shock (r = −0.172, r2 = 0.02973, p = 0.039)." (PMID 32492832, 2020). "This is a sterile model of sepsis that depends on RIPK1 kinase activity and RIPK3.42, 43 Sorafenib, administered by gavage 1.5 h before i.v. mTNF treatment, significantly protected mice from hypothermia and death caused by mTNF in a dose-dependent manner." (PMID 28661484, 2017). "Additionally, although our findings suggest that STING activation induces necroptosis, some studies have indicated that the RIPK3-MLKL necroptosis pathway can amplify STING signaling, aggravating sepsis progression." (PMID 40335920, 2025). "Furthermore, the plasma levels of necroptosis mediators, including high‐mobility group box‐1 (HMGB1), receptor‐interacting kinase 3 (RIPK3) and mixed‐lineage kinase domain‐like (MLKL) proteins, were well correlated with the severity and mortality in sepsis." (PMID 40318009, 2025). "In our study, neither TRAIL nor RIPK3 showed a direct association with AKI when adjusted for age, sex, disease severity (SOFA), sepsis, cardiovascular burden, and baseline eGFR." (PMID 41009652, 2025). "Additionally, RIPK3 and MLKL gene expression in circulating leukocytes has been positively correlated with sepsis-related mortality, further emphasizing the role of necroptosis in sepsis-induced lung injury." (PMID 40335920, 2025). "Similarly, raised p-RIPK3, RIPK3, and MLKL levels have been found in renal tissues of mouse models of sepsis resulting from cecal ligation and puncture (CLP)." (PMID 40817040, 2025). "Additionally, clinical studies have shown associations between the levels of necroptosis mediators, including receptor‐interacting kinase 1, RIPK3 and MLKL, and the severity and outcomes of sepsis." (PMID 40318009, 2025).
Sepsis (continued). "In addition, the positive feedback mechanism between the RIPK3/MLKL and GSDMD pathways and inflammation promotes the development of sepsis." (PMID 38684668, 2024). "Though necroptosis was initially posited as a driver of multiple inflammatory pathologies, including sepsis, evidence of widespread necroptosis in septic humans is lacking, and the hope of limiting septic inflammation by narrowly targeting the RIPK1 or RIPK3 kinase domain is likely misplaced." (PMID 38274794, 2023). "It’s reported that the inhibition of RIPK3 or RIPK1 could reduce systemic inflammation and organ damage in newborn mice with sepsis." (PMID 37091800, 2023). "Furthermore, the mtDNA copy number showed excellent correlations with those of necroptosis mediators, including RIPK3, MLKL, and HMGB1, which implies a link between plasma mtDNA and necroptosis in sepsis." (PMID 36289650, 2022). "Pharmacological inhibition of RIPK3 by GSK’872 accelerated the degradation of autophagosomes, induced the formation of autolysosomes, and thus alleviated tubular injury and improved renal function in sepsis-induced AKI." (PMID 36188562, 2022). "Excellent correlations between mtDNA level and necroptosis mediators (RIPK3, MLKL, and HMGB1) in this study show that a large proportion of plasma mtDNA may be released by necroptosis in sepsis." (PMID 36289650, 2022). "Receptor-interacting kinase 3 (RIPK3), a serine–threonine kinase implicated in non-caspase dependent apoptosis termed as necroptosis that leads to ARDS after trauma and sepsis; increased serum levels of RIPK3 are reported in morbid cases of COVID-19." (PMID 36143338, 2022). "We previously revealed that GSDMD-mediated pyroptosis and RIPK3-mediated necroptosis in both myeloid and nonmyeloid cells critically contributed to the progression of sepsis." (PMID 35941120, 2022). "Recently, the MESSI (Molecular Epidemiology of SepsiS in the Intensive care unit) trial, which is a prospective study with 120 patients, suggested a correlation between increased plasma levels of the necrosome-related RIPK3 and the development of ARDS during sepsis." (PMID 33791319, 2021). "We asked whether lung RIPK3 and MLKL expression are elevated following systemic LPS, which induces a systemic inflammatory state relevant to human sepsis and trauma, and whether plasma RIPK3 shows a concomitant rise." (PMID 31253195, 2019). "The RIPK3 level like the SOFA score and PCT level could be a prognostic biomarker of sepsis patients." (PMID 29137405, 2017). "Our data suggest that absence of RIPK3 also protects lungs from apoptotic cell death in ALI induced by sepsis." (PMID 24996547, 2014). "Since we observe almost no increase in liver-specific NK and CD8T cells after sepsis in the absence of RIPK3, it is reasonable to suggest that recruitment of these cell subsets to the liver is possibly associated with necrotopic liver damage." (PMID 24996547, 2014). "The previous study on polymicrobial sepsis in the absence of RIPK3 has only shown reduced systemic DAMPS, cytokines and LDH but did not investigate the organ specific damage." (PMID 24996547, 2014). "Furthermore, in the plasma mitochondrial DNA, a potent DAMP, the copy number was highly correlated with the essential necroptosis mediators, including RIPK3, MLKL and HMGB1, suggesting that mitochondrial DNA propagates necroptosis and increases the mortality rate due to sepsis in our previous study." (PMID 40318009, 2025). "In subgroup analyses restricted to patients with sepsis (n = 38), neither TRAIL nor RIPK3 plasma concentrations were significantly associated with in-hospital mortality (TRAIL: OR 1.02, 95% CI 0.99–1.05, p = 0.19; RIPK3: OR 1.00, 95% CI 0.999–1.0004, p = 0.31)." (PMID 41009652, 2025). "However, cohorts of septic patients do display increased expression of RIPK1, RIPK3 and MLKL, implying these mediators may be involved in sepsis progression." (PMID 38274794, 2023).
Sepsis (continued). "Nonetheless, it should be noted that this correlation between the TRAIL and RIPK3 proteins may not provide direct evidence that TRAIL reflects the process of necroptosis of sepsis." (PMID 32492832, 2020). "Fourth, the correlation between TRAIL and RIPK3 and its association with severity of sepsis does not provide sufficient evidence that TRAIL functions as an initiator of necroptosis in sepsis or necroptosis is activated in sepsis." (PMID 32492832, 2020). "We also note no change in the sepsis-induced decrease of various lymphocyte subsets in the thymus and spleen of Ripk3-/- mice in comparison with WT mice (data not shown), which suggests that the lymphocyte loss due to apoptosis does not depend on RIPK3-driven necroptosis in sepsis." (PMID 24996547, 2014). "Additionally, in experimental sepsis, where inflammation plays a key role, RIPK3, but not MLKL." (PMID 38077379, 2023). "Meanwhile, our study found that the concentration changes of plasma RIPK3 with time was similar to those of CRP levels, PCT levels, and SOFA score to monitor sepsis dynamically and then evaluate the severity of sepsis, which may be used for determining the prognosis of sepsis patients." (PMID 29137405, 2017). "Recently, RIPK3-dependent necrosis has been shown to be responsible for the mortality of septic mice induced either by TNF-α injection or polymicrobial sepsis, suggesting that targeting necrotic cells could be a novel and promising therapeutic approach for improving sepsis outcome." (PMID 24996547, 2014). "In the same vein, this study also showed that plasma RIPK3, MLKL, and HMGB1 levels were significantly higher in non-survivors than in survivors among critically ill patients with sepsis." (PMID 36289650, 2022). "While RIPK3 levels in sepsis patients as well as the RIPK1 levels in sepsis, severe sepsis, and septic shock patients did not remarkably change within 120 hours." (PMID 29137405, 2017). "However, unlike the previous study, our CLP-induced sepsis model shows much more severity with 100% mortality on day 2 after CLP in the WT mice group, and the Ripk3-/- mice group shows delayed mortality but still 100% mortality on day 6 after CLP." (PMID 24996547, 2014). "The concurrent elevation of RIPK-3, particularly in adult sepsis patients, although not statistically significant in children, aligns with animal and experimental data indicating that activation of RIPK(1/3) exacerbates tissue injury, cytokine release, and necroptotic cell death in sepsis models." (PMID 40722817, 2025).